PIP4K2C (phosphatidylinositol-5-phosphate 4-kinase type 2 gamma)
Description:
Phosphatidylinositol 5-phosphate 4-kinase with low enzymatic activity. May be a GTP sensor, has higher GTP-dependent kinase activity than ATP-dependent kinase activity. PIP4Ks negatively regulate insulin signaling through a catalytic-independent mechanism. They interact with PIP5Ks and suppress PIP5K-mediated PtdIns(4,5)P2 synthesis and insulin-dependent conversion to PtdIns(3,4,5)P3.
Synonyms: PIP5K2C; FLJ22055
Tractability: Small molecule: a structure with a bound ligand is known; a high-quality ligand is known; it has a high-quality binding pocket; it belongs to a druggable protein family. Antibody: its Gene Ontology location is reachable by antibodies, with high confidence. PROTAC: ubiquitination databases record sites on it; its protein half-life has been measured; a small molecule that binds it is known.
Target class: Enzyme; Transferase
Chemical probes: ARUK2001607 (high quality), SGC-PI5P4Kγ/MYLK4-1 (high quality), THZ-P1-2 (high quality), TM-04-176-01 (high quality)
Gene: Protein-coding gene on chromosome 12 (57,591,174 to 57,603,418, forward strand). Ensembl gene ENSG00000166908.
Subcellular location: Endoplasmic reticulum; Cytoplasm
Subcellular location (Human Protein Atlas): Cytosol; Nucleoplasm; Plasma membrane
Pathways (Reactome):
Metabolism: Synthesis of PIPs at the plasma membrane; Synthesis of PIPs in the nucleus
Signal Transduction: PI5P, PP2A and IER3 Regulate PI3K/AKT Signaling
Gene Ontology:
Molecular function: 1-phosphatidylinositol-4-phosphate 5-kinase activity; identical protein binding; protein binding; 1-phosphatidylinositol-5-phosphate 4-kinase activity; phosphatidylinositol kinase activity
Biological process: 1-phosphatidyl-1D-myo-inositol 4,5-bisphosphate biosynthetic process; negative regulation of insulin receptor signaling pathway; positive regulation of autophagosome assembly; regulation of autophagy; phosphatidylinositol phosphate biosynthetic process; phosphatidylinositol metabolic process
Cellular component: autophagosome; cytosol; extracellular exosome; cytoplasm; endoplasmic reticulum
Genetic constraint (gnomAD): Loss-of-function variants: 18 observed, 37.17 expected, observed/expected ratio (o/e) 0.48, 90% interval 0.33 to 0.72. The upper end of that interval is the gene's LOEUF score, 0.72, which puts it in group 2 of 6, group 1 being the genes least tolerant of losing a copy. Missense variants: 418 observed, 514.68 expected, observed/expected ratio (o/e) 0.81, 90% interval 0.75 to 0.88. Synonymous variants: 179 observed, 198.37 expected, observed/expected ratio (o/e) 0.9, 90% interval 0.8 to 1.02.
Homologues: Orthologues: chimpanzee PIP4K2C (99% identical), macaque PIP4K2C (99% identical), pig PIP4K2C (97% identical), guinea pig PIP4K2C (96% identical), rat Pip4k2c (96% identical), mouse Pip4k2c (96% identical), dog PIP4K2C (95% identical), tropical clawed frog pip4k2c (76% identical), zebrafish pip4k2ca (70% identical), zebrafish pip4k2cb (67% identical), rabbit PIP4K2C (54% identical). Paralogues in human: PIP4K2B (63% identical), PIP4K2A (62% identical), PIP5K1A (32% identical), PIP5K1C (30% identical), PIP5K1B (29% identical), PIP5KL1 (20% identical).
Diseases named in the same sentence as PIP4K2C in open-access papers:
PIP4K2C is named in the same sentence as 12 diseases in open-access papers, as found by Europe PMC text mining. Sharing a sentence is not in itself a finding about the gene and the disease. The quoted sentences say what the papers report.
acute myeloblastic leukaemia (2 papers, 2021 to 2023). "The functions of PIP4K2C are poorly known, although mutations suggest that this kinase could be involved in cell proliferation and acute myeloblastic leukaemia." (PMID 34421588, 2021).
cardiomyopathy (1 paper, 2024). A disease of the heart muscle or myocardium proper. "We consider the regulation of Pip4k2c, Ehmt2, Gper1, Dicer 1, Cul4b, Fyco1, Gn3l and TNNT2 in the context of doxorubicin-induced cardiomyopathy as particularly relevant." (PMID 39285385, 2024).
cancer (3 papers, 2023 to 2024). A tumor composed of atypical neoplastic, often pleomorphic cells that invade other tissues. "Interestingly, PIP4K2C expression has been associated with outcomes in Acute Myeloid Leukemia (AML), while CSNK2A2 has been associated significantly with prognoses of 14 different cancer types (Strum, Gyenis & Litchfield, 2022)." (PMID 38025707, 2023). "For example, the understudied “Dark” kinases PIP4K2C and CSNK2A2 appear in the top 25 features of the best-performing model, suggesting possible functional roles in cancer cell viability." (PMID 38025707, 2023). "Consequently, WX8 selectively terminates PIKFYVE-dependent cancer cells by virtue of its ability to selectively inhibit both PIKFYVE and PIP4K2C." (PMID 36803256, 2023).
tumor (2 papers, 2019 to 2024). "As a top feature specific to the P0119-T1 CAF model, perhaps PIP4K2C is a regulator of the tumor microenvironment due to its involvement with the immune system and cellular trafficking." (PMID 39221276, 2024). "Specifically, CSNK2A1/3 was identified as highly ranking in the P0422-T1 tumor line and the kinases CAMKK2 and PIP4K2C were identified in the P0119-T1 CAF line." (PMID 39221276, 2024).
PIP4K2C also shares sentences with these, for which no sentence is quoted: depression (1 paper); diabetes (1); fibrosis (1); Heart Disease (1); Huntington disease (1); melanoma (1); prostate carcinoma (1); viral infections (1).